RPS26P11 (ribosomal protein S26 pseudogene 11)
Synonyms: bA366E13.1; formerly RPS26L1
Gene: Processed pseudogene on chromosome X (72,044,545 to 72,044,892, forward strand). Ensembl gene ENSG00000196933.
Diseases named in the same sentence as RPS26P11 in open-access papers:
RPS26P11 is named in the same sentence as 1 disease in open-access papers, as found by Europe PMC text mining. Sharing a sentence is not in itself a finding about the gene and the disease.
RPS26P11 shares sentences with these, for which no sentence is quoted: diabetes (1 paper).